KLF8 (KLF transcription factor 8)
Diseases named in the same sentence as KLF8 in open-access papers (continued):
Sharing a sentence is not in itself a finding about the gene and the disease.
insomnia (1 paper, 2021). A sleep disorder characterized by difficulty in falling asleep and/or remaining asleep. "Klf8 was inactivated in antidepressant and insomnia treatments (sertraline, fluoxetine, suvorexant, imipramine, and 8beta) and strongly activated in neurotoxic conditions (Domo, Pb, and rb1 mutants)." (PMID 34211495, 2021).
invasive breast carcinoma (1 paper, 2016). A carcinoma that infiltrates the breast parenchyma. "The Pearson's correlation analysis identified the positive correlation of KLF8 and CXCR4 in invasive breast cancers, specifically in invasive ductal carcinoma (IDC) rather than invasive lobular carcinoma (ILC)." (PMID 26993780, 2016).
leukemia (1 paper, 2025). A malignant (clonal) hematologic disorder, involving hematopoietic stem cells and characterized by the presence of primitive or atypical myeloid or lymphoid cells in the bone marrow and the blood. "Four of these genes were reported for leukemias (IRS1, RUNX2, CCDC50 and ROBO3) and four others were reported to be involved in other types of cancers (NSG1, CAMK1D, CD3E, KLF8)." (PMID 41146244, 2025).
malignant glioma (1 paper, 2012). A grade III or grade IV glioma arising from the central nervous system. "Selective blocking of KLF8 might represent a novel anti-proliferative treatment strategy for malignant gliomas." (PMID 22276196, 2012).
melanoma (1 paper, 2018). A malignant, usually aggressive tumor composed of atypical, neoplastic melanocytes. "Given that KLF4 enhanced melanoma adaptation to ER stress, we first knocked down KLF4,KLF5 and KLF8 expression using shRNAs in Mel-RM and A375 cells." (PMID 30055641, 2018).
mental retardation (1 paper, 2014). "Abnormal expression of the KLF8 has been implicated in mental retardation." (PMID 25170845, 2014).
metastatic cancer (1 paper, 2015). A carcinoma which has spread from the original site of growth to another anatomic site. "To validate our findings in vivo, we detected FHL2 and KLF8 in serial sections of lymph node metastatic cancer tissues as exemplified in two patients." (PMID 26320172, 2015).
oral cancer (1 paper, 2013). "Hence, in this study we investigate the role of KLF8 in oral cancer and the effects of KLF8 knockdown via lentivirus mediated siRNA infection in human adenosquamos carcinoma cells (CAL 27)." (PMID 23722127, 2013). "A better understanding of KLF8 function and processing may provide novel insights into the clinical therapy of oral cancer." (PMID 23722127, 2013). "Furthermore, a better understanding of KLF8 function and processing may provide novel insights into the clinical therapy of oral cancer." (PMID 23722127, 2013). "Key words:KLF8, lentivirus, CAL 27, oral cancer, cell proliferation." (PMID 23722127, 2013). "However, silencing of KLF8 has not been explored in oral cancer cells." (PMID 23722127, 2013). "However, effects of KLF8 downregulation in human oral cancer invasion have not been investigated." (PMID 23722127, 2013).
prostate carcinoma (1 paper, 2017). A carcinoma that arises from epithelial cells of the prostate gland. "In this study, we show that prostate cancer-specific hypermethylation of the eight genes AOX1, CCDC181 (C1orf114), GABRE, GAS6, HAPLN3, KLF8, MOB3B, and SLC18A2 can be detected by qMSP with very high sensitivity and specificity in scarce prostate needle biopsy samples taken at the time of diagnosis." (PMID 28084441, 2017).
prostate tumors (1 paper, 2019). "(F) The correlation between RNA levels of GREB1, GHRHR and KLF8 and AR score in 333 TCGA primary prostate tumors were analyzed using Pearson’s correlation analysis (r)." (PMID 30644358, 2019). "Specifically, we found a statistically significant positive correlation (r) between GREB1 RNA level and AR output score across the primary prostate tumors from the TCGA dataset, but not GHRHR or KLF8." (PMID 30644358, 2019).
cancer (39 papers, 2013 to 2025). A tumor composed of atypical neoplastic, often pleomorphic cells that invade other tissues. "Particularly, KLF8, a transcription factor linked to cancer invasion and metastasis, demonstrated strong discriminatory potential and followed response dynamics in patients undergoing various systemic therapies." (PMID 40001235, 2025). "For example, CtBP2 associates with KLF8 (Kruppel-like factor 8) to activate the expression of Tiam1 (T-cell lymphoma invasion and metastasis 1), thereby promoting cancer cell migration." (PMID 32140068, 2020). "Overexpression of KLF8 has been reported to be highly correlated with decreased E-cadherin expression, which is associated with cancer cell invasion." (PMID 24604387, 2014). "Various signaling pathways regulating KLF8 expression and its target genes associated with cancer have been identified." (PMID 23722127, 2013). "Moreover, KLF8 is implicated in regulating cardiac disease, cancer, neuronal manipulation, and brain homeostasis." (PMID 39272379, 2024). "Importantly, KLF8 expression is elevated in various cancers, and is associated with increased invasiveness and metastasis." (PMID 37152043, 2023). "KLF8 is a transcription factor associated with oncogenic transformation in several cancers." (PMID 36846589, 2023). "Despite the discovery of an array of target genes and microRNAs of KLF8 that are associated with cancer and mechanisms regulating KLF8 at protein and subcellular levels, research on the molecular mechanisms by which KLF8 promotes metastasis remains in its infancy." (PMID 26993780, 2016). "The mechanism underlying KLF8 activation in cancer cells is yet to be elucidated." (PMID 24604387, 2014). "As Klf8 is an oncogene, its activation by neurotoxins may increase the risk of cancer." (PMID 34211495, 2021). "Overexpressed KLF8 in cancer cells contributes to tumor metastasis through extracellular matrix remodeling and increased angiogenesis." (PMID 38600248, 2024). "KLF8 is widely expressed in different tissues and has been confirmed to be aberrantly expressed in various cancers." (PMID 37864310, 2023). "Cancer cells, control or with altered KLF8 expression were analyzed to assess mammosphere formation efficiency, CSCs frequency and expression of CSCs factors." (PMID 37152043, 2023). "A previous study identified a critical role of OGT in promoting CSCs phenotype, and tumor initiation, potentially via upregulating cancer stem cell factors and upregulation of KLF8 levels." (PMID 37152043, 2023). "The expression levels of both NEDD4 and KLF8 were elevated in cancer tissues relative to those in adjacent normal tissues." (PMID 35031788, 2022). "KLF8 primes cells for metastasis by restricting a signalling pathway that would ordinarily inhibit migration and invasion by cancer cells." (PMID 35031788, 2022). "KLF8 has been reported to maintain the invasive capacity of cancer cells by inducing epithelial-to-mesenchymal transition (EMT)." (PMID 32411796, 2020). "As an important oncogene, KLF8 has drawn a lot of attention in the field of malignant tumors including HCC in recent years." (PMID 32874135, 2020). "Krüppel-like factor 8 (KLF8), a cancer-promoting factor that regulates critical gene transcription and cellular cancer-related events, has been implicated in tumor development and progression." (PMID 32874135, 2020). "As a KLF family member, KLF8 is often aberrantly expressed in many types of cancer and its overexpression is significantly correlated with oncogenic transformation." (PMID 32411796, 2020). "The impact of KLF8 expression on glycolysis, an altered energy metabolism that characterizes cancer cells, was evaluated." (PMID 31124603, 2019). "It is thus important to investigate if KLF8 plays a role in tumor angiogenesis and resistance to anti-cancer therapies such as radiotherapy and if CXCR4 is involved." (PMID 26993780, 2016).
cancer (continued). "It will be worth determining if KLF8-high cancer cells tend to colonize in these other CXCL12-high tissues in addition to the lungs." (PMID 26993780, 2016). "We showed that FHL2 and KLF8 were expressed at high and intermediate levels, respectively, in the cytoplasm and nucleus of cancer cells." (PMID 26320172, 2015). "KLF8 overexpression progressed from a pronounced increase in vector cells at day 21 to a 4-fold increase in the cancer area 35 days after injection." (PMID 26320172, 2015). "In this signaling model of tumor progression, the abnormally high expression of KLF8 in the cancer cells ensures the high level of EGFR." (PMID 26025929, 2015). "Another KLF member, KLF8 promotes human BC cell invasion and metastasis by transcriptionally repressing cadherin 1 (CDH1) and transactivating matrix metallopeptidase (MMP9), and high expression of KLF8 predicts a poor prognosis in human cancers." (PMID 25897424, 2015). "KLF8 is a GT-box binding dual-transcription factor, and KLF8 overexpression has been noted in a variety of aggressive human carcinomas." (PMID 26320172, 2015). "Increased KLF8 expression has been observed in several cancer tissues compared with that in normal tissues." (PMID 24604387, 2014). "KLF8 knockdown in the cancer cells resulted in reduced xenografted tumor growth in nude mice with decreased expression of cyclin D1 and Bcl-2, the upregulation of pro-apoptotic gene expression and apoptosis in the tumor cells." (PMID 23722127, 2013). "In addition, it is demonstrated that miRNA‐1236‐3p suppresses the proliferative ability and induces apoptosis of OS cells by downregulating KLF8, an important cancer‐promoting modulator." (PMID 39263604, 2024). "Similarly, the population of ALDH+ and NANOG-GFP+ CSCs in KLF8 overexpressing cancer cells was significantly increased compared to control cells." (PMID 37152043, 2023). "Previous studies have reported that KLF8 plays an important role in cancer chemoresistance." (PMID 37864310, 2023). "Hence, they demonstrated that KLF8 is a mediator of hypoxia-induced chemoresistance by increasing drug efflux from cancer cells and suppressing apoptosis in response to chemotherapeutics." (PMID 36846589, 2023). "Klf8 is a transcription factor that promotes cell cycle progression and can act as an oncogene by inducing proliferation and metastasis of cancer cells." (PMID 34211495, 2021). "In some types of cancer cells, KLF8 promoted the transformation and metastasis of the cancer cells." (PMID 31624471, 2019). "The roles of KLF8 in cancer biology was widely investigated." (PMID 31624471, 2019). "KLF8, which was also induced by SS, is expressed in several human cancers and is known to repress E-Cadherin transcription, thereby augmenting the motility and invasiveness of cancer cells." (PMID 30651129, 2019). "KLF8 induces epithelial-mesenchymal transition (EMT), a hallmark of cancer invasion and metastasis." (PMID 25853515, 2015). "It is reasoned that KLF8 could play a role in altering genomic integrity through aberrant DNA repair function and therefore contributing to the aggressive progression of cancer." (PMID 25853515, 2015). "Similar with FAK, KLF8 is ubiquitously expresses in invasive human cancer." (PMID 23722127, 2013). "Flow cytometry results revealed that KLF8-siRNA could induce an increase in G0/G1 phase cells and induce cancer cell apoptosis." (PMID 23722127, 2013). "Lentivirus-mediated silencing of KLF8 reduces cell proliferation and colonies number, thereby indicating the role of KLF8 in cell proliferation and tumorigenesis.Conclusions: These results strongly suggest that KLF8 is essential for growth of CAL 27 cancer cells." (PMID 23722127, 2013). "Herein, we sought to construct risk calculators based on cancer biomarkers, enabling more accurate discrimination among patients which may benefit from active interventions.Ki67 immunoscore, GSTP1 and KLF8 promoter methylation levels (me) were assessed in PCa tissues." (PMID 39090707, 2024).
cancer (continued). "Thus, the altered metabolism induced by KLF8 may be essential for cancer cell proliferation and metastasis." (PMID 31124603, 2019). "KLF8 directly binds the promoter region of miR‐429 to inhibit its expression, which targets SOX2 to mediate cancer stem cell‐like features in CD133+ OSCs." (PMID 39263604, 2024). "CPEB3, GHR, GSTZ1, and KLF8 were especially crucial molecules in the onset and progression of diseases and have been widely investigated in HCC or other forms of malignant tumors." (PMID 36827016, 2023). "KLF8 is highly expressed in OS tissues and highly enriched in CD133-positive cancer stem cell populations." (PMID 36499521, 2022). "The transcriptional factor Kruppel like factor 8 (KLF8) is involved in the initiation, progression, transformation, and metastasis of diverse cancers." (PMID 31624471, 2019). "Considering that KLF8 was highlighted to bind the promoter of MMP-9 to induce its expression and stimulate cancer invasion, thus we further examined the alterations of MMPs in the downstream of KLF8." (PMID 31827393, 2019). "Cell culture studies have demonstrated a critical role of KLF8 in promoting cell cycle progression, transformation, epithelial-to-mesenchymal transition (EMT), cancer stem cell induction and DNA-damage response." (PMID 26993780, 2016). "Observations using serial sections showed that KLF8 and FHL2 were distributed in both the nucleus and cytoplasm of the same cancer cells." (PMID 26320172, 2015). "To elucidate the correlation between KLF8 and FHL2 in cancer cells, we first checked the expression of these proteins in CRC cell lines by western blot." (PMID 26320172, 2015). "To validate our findings in vivo, we detected KLF8 and FHL2 expression in 13 pairs of adjacent normal colon mucosal tissues and cancer tissues by immunohistochemistry (IHC)." (PMID 26320172, 2015). "Krüppel-like factor 8 (KLF8) is a transcription factor that is highly overexpressed in ovarian and other cancers." (PMID 25605410, 2015). "Furthermore, silencing of KLF8 may lead to cancer cell death." (PMID 23722127, 2013). "KLF8 and KLF11 have also been shown to be involved in OS cancer stem cell induction." (PMID 36499521, 2022). "In addition, KLF8 induced tumor cell epithelial-to-mesenchymal transition (EMT) and maintained the invasive potential of cancer, which appeared to play a crucial role in the metastatic progression of human carcinomas." (PMID 26320172, 2015). "Importantly, we observed that high expression of KLF8 was associated with high TNM stage and metastasis, but not with cancer type." (PMID 31624471, 2019). "Importantly, the expression of KLF8 in normal tissues is much lower than that in cancer tissues and knockout of KLF8 is not embryonically lethal." (PMID 26993780, 2016). "The MCF10A overexpressing KLF8 alone, however, failed to form tumors, but unexpectedly underwent the epithelial to mesenchymal transition or EMT along with the induction of cancer stem-like cell traits." (PMID 25485290, 2014).
tumor (38 papers, 2012 to 2025). "Higher KLF8 expression associated with larger tumour size (P < 0.001), advanced T stage (P = 0.003) and N stage (P < 0.001)." (PMID 31124603, 2019). "KLF8 knockout lowers the capacity for tumour formation in vivo and prevents the formation of dense OS sarcoma spheres." (PMID 38546623, 2024). "KLF1, KLF5, and KLF8 promote tumor proliferation by activating the expression of the WNT/β-catenin pathway." (PMID 36761967, 2023). "We previously identified a critical role of OGT and O-GlcNAc in promoting CSCs phenotype and tumor initiation, potentially via upregulating KLF8 expression." (PMID 37152043, 2023). "Tumor growth in vivo of control or KLF8 knock-down cells was assessed by fat-pad injection of these cell in immunocompromised mice." (PMID 37152043, 2023). "In vivo findings verified that NEDD4 regulated the KLF8/miR-132/NRF2 axis by accelerating tumor growth and lung metastasis." (PMID 35031788, 2022). "The expression of NEDD4 and KLF8 was elevated in tumor tissues compared to that in adjacent normal tissues." (PMID 35031788, 2022). "miR-24-3p and KLF8, which are key regulators of the tumor immune microenvironment, had been proved to show metastasis-promoting property in LUAD." (PMID 32411796, 2020). "Here, we performed a systematic study of KLF family expression in hepatic metastases and matched primary tumours by RT‐PCR and found that KLF8 was significantly up‐regulated in liver metastases." (PMID 31124603, 2019). "The results showed that KLF8 expression was the most significantly up‐regulated among KLF members in liver metastases compared with primary tumours." (PMID 31124603, 2019). "KLF8 is critically involved in v-Src-induced transformation and plays a critical role in tumor progression." (PMID 31624471, 2019). "Our data showed that the expression of MMP-9 and MMP-2 was altered by DANCR/miR-135a-5p/KLF8 axis, which just further proved the regulatory network on tumor malignancies from the point of molecular level." (PMID 31827393, 2019). "KLF8 showed the highest up‐regulation in liver metastases compared with primary tumours among all KLF members." (PMID 31124603, 2019). "KLF8 is aberrantly expressed in several types of human tumours and its high expression is significantly correlated with oncogenic transformation and tumour progression." (PMID 31124603, 2019). "A CAM model and a nude mouse tumor model indicated that KLF8 up-regulation in HCC cells had a higher potential for inducing angiogenesis." (PMID 30479372, 2018). "Tumor tissue sections were prepared, and immunoreactivity was analyzed as above using KLF8, VEGF and CD31 antibodies (BD PharMingen)." (PMID 30479372, 2018). "We demonstrate that KLF8 plays a critical role in both invasive growth of the local primary tumor and the lung metastasis in a CXCR4-dependent manner." (PMID 26993780, 2016). "Xenograft studies showed that overexpression of CXCR4, but not a dominant-negative mutant of it, in the MDA-MB-231 cells prevented the invasive growth of primary tumor and lung metastasis from inhibition by knockdown of KLF8." (PMID 26993780, 2016). "Since miR141 and miR200c share the same promoter and KLF8 strongly represses this promoter, it is likely that the regulation of miR200c and ZEB1 by KLF8 also contributes to the overall outcomes of the tumor progression." (PMID 26025929, 2015). "The tumor volumes of the KLF8-overexpressing cells were markedly greater than those of the vector-expressing cells." (PMID 26320172, 2015). "Third, our data showed that KLF8 had a critical role in FHL2-mediated tumor growth, EMT and metastatic phenotypes in vitro and in vivo." (PMID 26320172, 2015). "qPCR analysis confirmed the overexpression of miR141 in the 231-K8ikd-miR141 cells as well as the upregulation of the endogenous miR141 upon KLF8 knockdown in the tumor tissue." (PMID 26025929, 2015). "We found that the tumor growth was inhibited comparably by the knockdown of KLF8 and the overexpression of miR141 (U + miR141)." (PMID 26025929, 2015).